VHL (von Hippel-Lindau tumor suppressor)
Diseases named in the same sentence as VHL in open-access papers (continued):
Sharing a sentence is not in itself a finding about the gene and the disease.
breast carcinoma (continued). "CBD can suppress angiogenesis and stem cell-like properties of breast cancer through Src/VHL/HIF-1α signaling." (PMID 34830821, 2021). "The aim of this study was to assess the effects of CBD for the angiogenesis and stemness of breast cancer cells by decreasing the expression of hypoxia-induced factor-1α (HIF-1α) through the Src/von Hippel–Lindau tumor suppressor protein (VHL) interaction." (PMID 34830821, 2021). "miR-155 induces angiogenesis by regulating VHL in breast cancer and is related to poor outcomes among breast cancer patients." (PMID 32958011, 2020). "LincRNA-p21 is inducible by hypoxia or HIF1α function in breast cancer cells, and binds to HIF1α and its E3 ubiquitin ligase von Hippel-Lindau (VHL), thereby disrupting the VHL-HIF1α interaction." (PMID 33123488, 2020). "In vitro studies have demonstrated that VHL has inhibitory effects on the invasive and migratory ability of breast cancer cells." (PMID 27540529, 2016). "We notified that UA increases VHL mRNA expression in breast cancer cells, which leads a low level of HIF-1α and HIF-2α." (PMID 27708244, 2016). "In contrast, HIF1a downregulation by VHL over-expression, anti-miR-101 oligo administration or 2-MeOE2 treatment rescued cells from miR-101-mediated apoptosis and cell cycle arrest in breast cancer cells." (PMID 26841847, 2016). "Most interestingly, it was recently shown that miR-155 targets VHL tumor suppressor and promotes angiogenesis in breast cancer." (PMID 24849932, 2014). "When leaving out age and using the Pearson chi-square test, methylation in PTEN and VHL was also significantly less common in male breast cancer (P = 0.029 and P = 0.025, respectively)." (PMID 22765268, 2012). "In addition, for TTM involving meningiomas and breast cancer or VHL-related HGB, hormonal or genetic factors have been suggested as contributing mechanisms." (PMID 40726878, 2025). "These patients were found to have pathogenic germline variants in the VHL gene, after undergoing genetic testing for other purposes (5 for familial breast cancer risk and 1 to determine ancestry) but no VHL disease-associated tumors." (PMID 40063608, 2025). "Moreover, our recent findings indicate that UBE3B promotes breast cancer growth and metastasis by counteracting VHL-mediated HIF-2α degradation." (PMID 38914543, 2024). "Together, these results suggest that VHL may regulate UBE3B protein stability in breast cancer cells." (PMID 38914543, 2024). "Taken together, VHL regulates UBE3B protein stability in breast cancer cells." (PMID 38914543, 2024). "Given the established role of UBE3B as an oncoprotein in breast cancer and its regulation by VHL, we sought to examine whether VHL could inhibit UBE3B-mediated breast cancer cell proliferation, survival, and invasion." (PMID 38914543, 2024). "Our current findings uncovered that VHL is a bona fide E3 ligase for UBE3B in breast cancer." (PMID 38914543, 2024). "In addition, we showed that UBE3B overexpression robustly attenuates VHL’s inhibitory effects on breast cancer cell proliferation, colony formation, and invasion in vitro, and breast tumor growth and lung metastasis in mice." (PMID 38914543, 2024). "Here, we found the VHL gene in breast cancer is largely wild-type by analyzing cBioPortal database." (PMID 36813923, 2023). "We further verified the effects of hypoxia enhancing miRNA-induced oxidative stress, cell migration, induction of EMT, expression of hypoxia-linked genes such as VHL, HIF-1α, and NFκB1, and expression of inflammation-associated genes such as VEGFA, COX-2, and EP4 in breast cancer cell lines." (PMID 32707933, 2020). "Thus, we conclude that miR-183 enhances the stability of HIF1α through targeting VHL mRNA CDS in breast cancer cells." (PMID 26309161, 2015). "The expression of unhydroxylated HIF-1α positively correlates with VHL in breast cancer suggesting that VHL may be rate-limiting for HIF degradation." (PMID 24563687, 2014).
breast carcinoma (continued). "Therefore, identifying novel VHL substrates could benefit the clinical outcome of breast cancer patients." (PMID 38914543, 2024). "Therefore, the development of VHL-based PROTACs targeting UBE3B may offer potential benefits for breast cancer patients." (PMID 38914543, 2024). "Based on RNA-seq data from The Cancer Genome Atlas and several Gene Expression Omnibus datasets, a 14-gene hypoxia-related signature, which included VHL, was developed and the findings revealed that this signature could serve as a potential prognostic biomarker for breast cancer." (PMID 36036061, 2023). "However, the study of VHL status and expression in breast cancer is limited so far." (PMID 36813923, 2023). "Taken together, VHL promotes UBE3B and subsequent HIF-2α degradation and consequently inhibits the oncogenic potential of breast cancer cells." (PMID 38914543, 2024). "A recent study has shown that CBD can inhibit breast cancer growth by inhibiting SRC activity, thereby upregulating VHL expression, reducing HIF-1α synthesis in breast cancer cells, and inhibiting angiogenesis." (PMID 38731434, 2024). "To explore the potential relevance of VHL and UBE3B in human breast cancer, we extracted cell lysates from breast tumors and adjacent normal breast tissues for western blotting." (PMID 38914543, 2024). "VHL promotes the ubiquitination and degradation of UBE3B, which stabilizes the oncoprotein HIF-2α in breast cancer." (PMID 38914543, 2024). "Our study discovered the VHL gene is largely wild-type in breast cancer and validates the therapeutic benefits of pVHL in TNBC, the most lethal subtypes of human breast cancers with limited therapeutic options." (PMID 36813923, 2023). "Ms4322 is a PROTAC drug based on VHL, which can highly selectively reduce PRMT5 in breast cancer, cervical cancer, lung cancer, leukemia cells, and ER+ breast cancer cells and inhibit the growth of cancer cells." (PMID 36770884, 2023). "In breast cancer, other studies reveal miR-210 is regulated by hypoxia via HIF-1α/VHL transcriptional system." (PMID 35346372, 2022). "CBD inhibits Src activity, which decreases HIF-1α through the degradation of VHL recruitment and the direct reduction of HIF-1α protein synthesis in mammospheres as well as breast cancer cells." (PMID 34830821, 2021). "Previous studies have indicated that the E3 ligase VHL and FOXB33 promoted KLF4 degradation in breast cancer." (PMID 30658712, 2019). "This is apparently the opposite of the observation from breast cancers, where DEC2 promoted VHL-independent degradation of HIF-1α." (PMID 25884381, 2015). "In male breast cancer, methylation was very rare in BRCA1, CDKN2A, VHL, ATM and CHFR (< 2%) - indicating that methylation of these genes does not seem to play a prominent role in male breast carcinogenesis." (PMID 22765268, 2012). "TTM should be considered in patients with a history of breast cancer and atypical CNS lesions, even without VHL." (PMID 40726878, 2025). "The three co-opted E3 ligases, VHL, XIAP, and AHR, have been explored against cancer targets in PROTAC12,22,44–46, and their expression patterns in tumor and normal tissues suggest extensive future usage, such as XIAP in breast cancer." (PMID 37845222, 2023). "Therefore, CBD can attenuate Src/VHL/HIF-1α signaling and inhibit angiogenesis, followed by inhibiting the growth and invasion of breast cancer and cancer stem-like properties." (PMID 34830821, 2021).
breast carcinoma (continued). "Thus, it could be understood that CBD can inhibit the aggressiveness of breast cancer and be sensitized to more aggressive breast cancer cells by regulating a variety of signaling pathways and immunologic factors related to malignancy as well as Src/VHL/HIF-1α signaling." (PMID 34830821, 2021). "In concordance with our previous results, high ∆Np73 levels did not correlate with any significant changes in VHL or HIF-1α mRNA levels in the breast cancer patients." (PMID 29628507, 2018). "SHARP1 has been reported to be a crucial regulator in the proteasomal degradation of HIF-1α for breast cancer progression without pVHL (von Hippel-Lindau tumor suppressor), hypoxia, and the ubiquitination mode." (PMID 28903320, 2017). "Since there was simultaneous upregulation of anti-angiogenic VHL and pro-angiogenic VEGF, CAM assay was employed as a means to directly asses the angiogenic potential of macrophages incubated with culture supernatant of normoxic or hypoxic breast cancer cells." (PMID 25051364, 2014). "Furthermore, VHL-mediated UBE3B downregulation in breast cancer cells could be restored by the proteasome inhibitor MG132, indicating that VHL modulates UBE3B protein levels through the proteasomal system." (PMID 38914543, 2024). "Importantly, the protein levels of UBE3B and VHL exhibit a negative correlation in breast cancer tissues." (PMID 38914543, 2024). "Additionally, the protein levels of UBE3B and VHL exhibit a negative correlation in breast cancer tissues." (PMID 38914543, 2024). "Similarly, PROTACs using biochemical inhibitors were designed to tag SGK3 kinase with VHL ubiquitin ligases to facilitate selective and efficient degradation of SGK3 in breast cancers compared to conventional inhibitors because of their sub-stoichiometric catalytic mode of action." (PMID 34552611, 2021). "As expected, the results showed that about 45% of breast cancer cells displayed a negative correlation between the protein levels of UBE3B and VHL." (PMID 38914543, 2024). "We observed decreased VHL protein levels in tumors, coinciding with upregulated UBE3B protein levels, suggesting a negative correlation between the protein levels of VHL and UBE3B in breast cancer." (PMID 38914543, 2024). "CoCl2-induced hypoxia in breast cancer further promotes HIF-1α mRNA and protein expression while reducing VHL expression (a negative HIF-1α regulator), especially in miRNA-high cell lines." (PMID 32707933, 2020). "Finally, VHL and SHARP1 have been selected as two putative tumor suppressor genes in breast cancer with indicated negative effects on the expression of HIF." (PMID 27540529, 2016).
paraganglioma (59 papers, 2010 to 2026). A benign or malignant neoplasm arising from paraganglia located along the sympathetic or parasympathetic nerves. "VHL type 1 pathogenic alleles strongly affect VHL protein function and are associated with a relatively low risk of paragangliomas." (PMID 38390862, 2024). "VHL type 2 PVs are missense mutations, which result in less severe alteration of VHL properties and render a high probability of paraganglioma development." (PMID 38390862, 2024). "For example, almost all VHL disease families that develop paraganglioma have missense VHL mutations." (PMID 39320914, 2024). "VHL families are said to have type 1 disease if they display a low risk of paraganglioma and type 2 disease if they display a high risk of paraganglioma." (PMID 36106637, 2022). "In conclusion, we report the first diagnosis of a functional mediastinal paraganglioma in a young patient with a missense mutation in exon 1 of the VHL gene." (PMID 29789510, 2018). "In addition, HIF2α has been shown to be constitutively activated in paragangliomas with VHL mutations; accordingly, such tumors were also shown to harbor mutations associated with unregulated activity of HIF2α." (PMID 28187001, 2017). "Similarly, elevated HIF1α activity has only been demonstrated in a study of paragangliomas carrying a VHL mutation." (PMID 28187001, 2017). "Functioning SDHx paragangliomas sometimes release dopamine and/or norepinephrine, originating raised plasma levels of methoxytyramine, contributing to distinguish SDHx patients from those with VHL, RET, or NF1 mutations." (PMID 24899893, 2014). "Paragangliomas may occur sporadically or in hereditary syndromes associated or caused by VHL and SDHB mutations." (PMID 22344361, 2012). "The paraganglioma tumors were SDH-deficient and, therefore, excluded from the list of VHL-related tumors." (PMID 40647474, 2025). "RET and VHL are HSP90 clients, and it has been reported that the expression of HIF-1α and HIF-2α (an HSP90 client) were implicated in the pathogenesis of paraganglioma with SDHB and SDHD mutations." (PMID 35932386, 2022). "This particular characteristic was widely described in the subgroup of pheocromocytoma and paraganglioma carrying mutations in SDH genes and VHL, often classified as a pseudo-hypoxic cluster." (PMID 33806389, 2021). "Sporadic panNETs arose in 141 patients with panNET-associated familial syndromes in 42 individuals: 36 with MEN1, 2 with VHL, 1 each with TSC, NF1, paraganglioma, MAX mutation and MUTYH-associated polyposis." (PMID 34163434, 2021). "In paraganglioma, four studies found higher PET SUV-values for SDHx-mutated tumors or SHDx and VHL-mutated tumors, relevant for heritability risk assessment." (PMID 29732009, 2018). "The prevalence of germline mutations in SDHB, SDHC, SDHD, VHL and MAX in PCC and paraganglioma patients is, respectively, 10%, 1%, 9%, 7%, and 1%." (PMID 29768630, 2018). "Group I comprises subgroup 1A, including paragangliomas with mutations in the SDH and fumarate hydratase (FH) genes, and subgroup 1B, representing those with mutations in the HIF2A and VHL genes." (PMID 28187001, 2017). "To investigate the extent and nature of chromosome 11 loss across the various paraganglioma subgroups, we assembled a panel of 26 SDHD, 13 SDHB, and 8 VHL-related PGLs/PCCs." (PMID 28099933, 2017). "Germline mutations have been identified in paragangliomas involving the proto-oncogene RET, tumor suppressor genes VHL, and NF1 The commonest clinical presentation is hypertension but incidentally detected forms have been reported during imaging and on a few occasions the diagnosis was missed." (PMID 36591002, 2022). "This dataset has the advantage of including not only HNPGL with or without SDH mutations, but also HNPGL carrying somatic VHL mutations, which are highly infrequent in paraganglioma of parasympathetic linage." (PMID 35740651, 2022). "Rare thoracic paragangliomas have been known to be associated with SDHB, SDHD, and VHL genes." (PMID 36138281, 2022).
paraganglioma (continued). "Additionally, in several recorded cases, paragangliomas violated the “mutual exclusion of mutations” rule: these tumors simultaneously carried somatic mutations in the NF1 gene and in the RET or VHL genes." (PMID 28187001, 2017). "To further clarify the role of loss of the maternal copy of 11p in relation to loss of the long arm of chromosome 11 in paragangliomas, we used several genetic approaches to determine the allelic status of chromosome 11 in SDHAF2, SDHD, SDHB, and VHL mutant PGLs/PCCs." (PMID 28099933, 2017). "Mutations in the VHL and NF1 genes are also associated with inherited paragangliomas." (PMID 20205783, 2010). "The difference was even wider among the patients with VUS variants: 71% (57/80) had only non-VHL component tumors, 23% (18/80) had no tumors, and 5% (4/80) and 1% (1/80) had isolated RCC and isolated paraganglioma, respectively." (PMID 40647474, 2025). "Given the lack of human paraganglioma cell lines, we studied the effects of inactivating VHL in neuroblastoma cell lines, which also arise from the sympathetic nervous system." (PMID 39320914, 2024). "Both paraganglioma and cystadenoma were never found as single VHL phenotypes, suggesting that these two tumors arise as secondary manifestations of VHL, possibly pairing pVHL impairment with the functional inactivation of other relevant players." (PMID 30943211, 2019). "Nenhuma alteração genética dos genes VHL e SDHB foi detectada nos tecidos tumorais e adjacentes ao tumor, o que nos levou a afastar uma síndrome hereditária que poderia explicar a associação entre o paraganglioma e o CCRC em um paciente com hipertensão arterial." (PMID 22344361, 2012).